RN7SKP6 (RN7SK pseudogene 6)
Gene: Miscellaneous RNA gene on chromosome 13 (56,885,284 to 56,885,602, reverse strand). Ensembl gene ENSG00000201665.
Homologues: Orthologues: chimpanzee 7SK (99% identical), guinea pig 7SK (64% identical). Paralogues in human: RN7SKP180 (74% identical), RN7SKP71 (74% identical), RN7SKP124 (74% identical), RN7SKP78 (74% identical), 7SK (73% identical), RN7SKP255 (73% identical), RN7SKP90 (73% identical), RN7SKP3 (73% identical), RN7SKP79 (73% identical), RN7SKP176 (72% identical), RN7SKP208 (72% identical), RN7SKP250 (72% identical), and 284 more.